FOXF2 (forkhead box F2)
Description:
Probable transcription activator for a number of lung-specific genes. Mediates up-regulation of the E3 ligase IRF2BPL and drives ubiquitination and degradation of CTNNB1.
Synonyms: FREAC-2; FKHL6; FREAC2
Tractability: PROTAC: ubiquitination databases record sites on it.
Safety:
Unwanted effects reported when the protein is acted on. In parentheses: how it was acted on, where the effect was seen, and who reports it.
agranulocytosis (source: ClinPGx)
Gene: Protein-coding gene on chromosome 6 (1,389,576 to 1,395,603, forward strand). Ensembl gene ENSG00000137273.
Subcellular location: Nucleus
Subcellular location (Human Protein Atlas): Nuclear bodies; Nucleoplasm; Vesicles
Gene Ontology:
Molecular function: DNA binding; DNA-binding transcription activator activity, RNA polymerase II-specific; DNA-binding transcription factor activity; general transcription initiation factor binding; RNA polymerase II transcription regulatory region sequence-specific DNA binding; sequence-specific DNA binding; TFIIB-class transcription factor binding; DNA-binding transcription factor activity, RNA polymerase II-specific; RNA polymerase II cis-regulatory region sequence-specific DNA binding
Biological process: genitalia development; positive regulation of DNA-templated transcription; positive regulation of transcription by RNA polymerase II; regulation of proteasomal ubiquitin-dependent protein catabolic process; regulation of protein polyubiquitination; roof of mouth development; animal organ morphogenesis; epithelial to mesenchymal transition; regulation of transcription by RNA polymerase II; embryonic camera-type eye morphogenesis; regulation of DNA-templated transcription; system development
Cellular component: nuclear body; nucleoplasm; nucleus; transcription regulator complex; chromatin
Genetic constraint (gnomAD): Loss-of-function variants: 13 observed, 20.34 expected, observed/expected ratio (o/e) 0.64, 90% interval 0.41 to 1.02. The synonymous counts are far from expectation, so gnomAD's model fits this gene poorly and the ratio says little. Missense variants: 533 observed, 470.38 expected, observed/expected ratio (o/e) 1.13, 90% interval 1.05 to 1.22. Synonymous variants: 263 observed, 210.2 expected, observed/expected ratio (o/e) 1.25, 90% interval 1.13 to 1.39.
Homologues: Orthologues: macaque FOXF2 (99% identical), chimpanzee FOXF2 (99% identical), mouse Foxf2 (94% identical), pig FOXF2 (93% identical), rabbit FOXF2 (90% identical), rat Foxf2 (83% identical), zebrafish foxp1b (20% identical), zebrafish foxp1a (18% identical). Paralogues in human: FOXP2 (21% identical), FOXP4 (20% identical), FOXI1 (18% identical).
Diseases named in the same sentence as FOXF2 in open-access papers:
FOXF2 is named in the same sentence as 66 diseases in open-access papers, as found by Europe PMC text mining. Sharing a sentence is not in itself a finding about the gene and the disease. The quoted sentences say what the papers report.
breast carcinoma (33 papers, 2012 to 2025). "We obtained ChIP-seq data of the candidate transcription factors FOSB (ENCSR569XNP), ZNF302 (ENCFF037UPH), SP1 (ENCFF072FPF), ELK1 (ENCFF123KER), and FOXF2 (ENCFF008ABX) in a breast cancer cell line MCF-7 from ENCODE." (PMID 37173692, 2023). "The increased autocrine and paracrine TGF‐β signaling in the mesenchymal transcription factor forkhead box F2 (FOXF2) deficient base‐like breast cancer cells induces EMT to mediate tumor metastasis." (PMID 34977870, 2021). "In this study, we further characterized the role of FOXF2 in metastasis of basal-like breast cancer (BLBC) and underlying molecular mechanisms." (PMID 25848863, 2015). "Collectively, these results suggest that FOXF2 deficiency enhances the metastatic potential of basal-like mammary epithelial cells and breast cancer cells but reduces cell proliferation." (PMID 25848863, 2015). "Results showed that FOXF2 mRNA levels in primary breast cancer were negatively associated with tumor progression, including tumor size, number of metastatic lymph nodes, and clinical stage." (PMID 23620774, 2013). "Although the low expression of FOXF2 is associated with prostate cancer, the role of FOXF2 in breast cancer is still unclear." (PMID 23620774, 2013). "Comparison of recrudescence and metastasis risk between different FOXF2 mRNA levels and clinicopathological features in breast cancer patients." (PMID 23620774, 2013). "Our data suggest that patients with low FOXF2 mRNA levels have a high risk of early-onset relapse and metastasis, and in histological grade II breast cancer, FOXF2 mRNA levels in primary cancer tissues predict the prognosis of patients." (PMID 23620774, 2013). "Association between FOXF2 mRNA levels in primary breast cancer tissues and clinicopathological variables." (PMID 23620774, 2013). "Furthermore, low Foxf2 expression has been reported to correlate with early-onset metastasis and poor prognosis in breast cancer patients, and loss of Foxf2 expression promotes an EMT and metastasis of experimental cancer." (PMID 30285803, 2018). "However, the role of FOXF2 in breast cancer metastasis and the underlying molecular mechanisms remain largely unknown." (PMID 25848863, 2015). "In fact, FOXF2 has a similar effect on visceral metastasis in addition to playing a role in bone metastasis of breast cancer." (PMID 40003882, 2025). "In luminal breast cancer cells, FOXF2 initiates the recruitment of NCoA3, forming a complex that attaches to the WNT2B and FZD1 promoters." (PMID 40003882, 2025). "FOXF2 is minimally expressed in lumenal breast cancer and promotes the proliferation of cancer cells, while it is highly expressed in BLBC and reduces the stemness of cancer cells." (PMID 40003882, 2025). "In luminal and HER2-positive breast cancer, FOXF2 is believed to play a major role in regulating the cell cycle." (PMID 40003882, 2025). "Associated with multiple transcription corepressor complexes, FOXF2 can repress the tumorigenesis and hypoxic response of breast cancer, and during the progression of breast cancer, FOXK2 expression is progressively lost." (PMID 40003882, 2025). "Much like FOXC1, FOXF2 also exhibits a dual role in breast cancer, with its function significantly differing between the luminal and basal types of the disease." (PMID 40003882, 2025). "For example, it was recently shown that FOXF2 functions as a Wnt pathway inhibitor in basal-like breast cancer cells but that it activates Wnt signaling in luminal breast cancer." (PMID 37011861, 2023). "SP-1 can bind with FOXF2 promoter region and block the DNA methylation of FOXF2 in breast cancer cells, leading to promotion of cell proliferation in basal-like breast cancer." (PMID 35620052, 2022). "In turn, TGF‐β silences FOXF2 expression by up‐regulating the post‐transcriptional regulator (miR‐182‐5p) of FOXF2 and promotes breast cancer metastasis." (PMID 34977870, 2021).
breast carcinoma (continued). "While recent in vitro study suggested that FOXF2 binds to the promoter and represses the expression of FOXQ1 in a breast cancer cell line, our in vivo data demonstrated a cis-regulation of Foxq1 expression by the Foxf2 gene disruption." (PMID 33898467, 2021). "FOXF2 inhibits proliferation, invasion, migration, metastasis and drug resistance of breast cancer cells." (PMID 32503970, 2020). "Many functions of FOXF2 in breast cancer are depend on the internal environment of cells and tissues." (PMID 32503970, 2020). "One study showed that miR-200c can inhibit the metastasis of breast cancer cells and significantly reduce FOXF2 expression." (PMID 32503970, 2020). "MiR-301 is thought to be a breast cancer oncomiR, which promotes tumor invasion and nodal or distant relapses via direct interaction with FOXF2, PTEN, BBC3iso-2, and COL2A1." (PMID 32605588, 2020). "Since breast cancer cells with osteomimetic features have the advantage of osteotropism, we analyzed the relationship between the expression of FOXF2 and BRGs in primary breast cancer tissues with bone-only metastasis based on the GSE2034_GSE2603 data set." (PMID 31222004, 2019). "In this study, we found that FOXF2 is ectopically coexpressed with a set of BRGs in primary breast cancer tissues." (PMID 31222004, 2019). "We showed that the mesenchymal TF FOXF2, which is ectopically expressed in breast cancer cells, drives breast cancer cells to develop into bone metastasis seeds by directly programming the EOT." (PMID 31222004, 2019). "To provide clinical evidence validating the role of CTSK and the FOXF2-CTSK axis in breast cancer bone metastasis, we analyzed CTSK expression levels in metastatic tissues in bone and other organs based on the GSE14020 data set." (PMID 31222004, 2019). "FOXF2 mRNA levels in primary breast cancer tissues that developed distant metastasis were detected by reverse transcription–quantitative polymerase chain reaction (RT-qPCR)." (PMID 31222004, 2019). "The BMP antagonist Noggin significantly inhibits FOXF2-driven osteolytic bone metastasis of breast cancer cells." (PMID 31222004, 2019). "We further validated the role of Foxf2 in regulating breast cancer metastasis using a 4T1/BALB/c orthotopic xenograft mouse models with Foxf2 loss- and gain-of-function." (PMID 31222004, 2019). "Together, these clinical data support the role of the FOXF2/BMP/SMAD axis in breast cancer bone metastasis." (PMID 31222004, 2019). "To investigate the role of FOXF2 in regulating various processes underlying breast cancer bone metastasis, we forced the ectopic expression of FOXF2 in MCF-7 cells and overexpressed or knocked down FOXF2 in MDA-MB-231 cells." (PMID 31222004, 2019). "To investigate the role of FOXF2 in regulating breast cancer bone metastasis, we established 4T1 cells stably overexpressing Foxf2–Flag fusion protein (4T1-Foxf2) and their controls (4T1-Vector) via lentiviral infection for mouse xenograft experiments." (PMID 31222004, 2019). "Then, we analyzed the relationship between FOXF2 expression and organ specificity of metastasis in the luminal and triple-negative subtypes of breast cancer." (PMID 31222004, 2019). "Their further research also showed that FOXF2 promoted basal-like breast cancer cells metastasis by up-regulation of TWIST1 as well as activating EMT." (PMID 30249755, 2018). "Interestingly, Foxf2 expression was significantly higher in more aggressive tumor subtypes, such as ER– compared with ER+, triple-negative compared with all other subtypes, and in claudin-low tumors (the breast cancer subtype associated with an EMT signature), compared with all others." (PMID 30285803, 2018). "Although Foxf2 expression was not predictive for metastasis formation or survival in the total patient pool, high expression of Foxf2 correlated with poor overall survival in patients with luminal subtype B breast cancer." (PMID 30285803, 2018).
breast carcinoma (continued). "Here, we have employed a TGFβ-induced EMT in NMuMG cells and in murine and human breast cancer cells to demonstrate a critical role of Foxf2 during an EMT by concomitantly regulating an EMT, cell survival, and apoptosis." (PMID 30285803, 2018). "Comparably, low Foxf2 expression has been recently reported to correlate with early-onset metastasis and poor prognosis in breast cancer patients." (PMID 30285803, 2018). "To further substantiate a potential correlation between Foxf2 expression and patient survival, we analyzed the Netherlands Cancer Institute (NKI295) breast cancer database for Foxf2 expression." (PMID 30285803, 2018). "The mechanistic insights into Foxf2 functions also support a dual role of Foxf2 in breast cancer progression and metastasis, on one hand by affecting cell junction homeostasis, and by regulating cell proliferation and survival on the other hand." (PMID 30285803, 2018). "To support the importance of a Foxf2 function during tumor development and progression, we have performed correlation studies for Foxf2 on three different breast cancer databases." (PMID 30285803, 2018). "a novel EMT-suppressing transcription factor in basal-like breast cancer (BLBC), FOXF2 deficiency enhances metastatic ability of BLBC cells by activating the EMT program through upregulating the transcription of TWIST1." (PMID 28121627, 2017). "In our previous study, we found that FOXF2 is a novel EMT-suppressor and decreased FOXF2 is associated with poor prognosis of patients with basal-like breast cancer." (PMID 27487137, 2016). "And in breast cancer FOXF2 is a target gene of miR-301, which acts as a crucial oncogene to promote metastatic tumor progression." (PMID 27487137, 2016). "The regulatory mechanisms of the different expression pattern and functions of FOXF2 in basal-like and luminal breast cancer cells should be further deeply investigated." (PMID 25848863, 2015). "A series of in vitro and in vivo assays was performed in the cells with RNAi-mediated knockdown or overexpression to elucidate the function and transcriptional regulatory role of FOXF2 in breast cancer." (PMID 25848863, 2015). "Recent studies have indicated that FOXF2 is a potential tumor suppressor in both prostate cancer and breast cancer." (PMID 25848863, 2015). "Mechanism dissection indicated that the miR301a promoted breast cancer proliferation and metastasis via targeting FOXF2, BBC3, PTEN, and COL2A1, as well as down-regulated NF-kB-repressing factor and elevated NF-kB activation in human pancreatic adenocarcinoma." (PMID 25940439, 2015). "The clinical value of changes in FOXF2 mRNA levels in breast cancer tissue and in other type of cancers should be further evaluated and confirmed by large multicenter studies." (PMID 23620774, 2013). "In this study, we explored the correlation between FOXF2 mRNA expression and tumor progression and metastasis, as well as its prognostic value for patients with breast cancer." (PMID 23620774, 2013). "Recently miR-301 was defined as an oncogene and it was reported to mediate proliferation via regulating FOXF2 in breast cancer." (PMID 23383207, 2013). "Expression of FOXF2 is decreased in prostrate cancer, and FOXF2 is a target gene of miR-301, which acts as a crucial oncogene in breast cancer to promote metastatic tumor progression." (PMID 23620774, 2013). "Our studies revealed that decreased FOXF2 mRNA expression is an intrinsic marker of early-onset relapse and metastasis of breast cancer, and independently predicts poor prognosis for patients with histological grade II and triple-negative breast cancer." (PMID 23620774, 2013). "In this study, we showed that decreased FOXF2 mRNA levels in primary breast cancers negatively correlate with tumor progression, including tumor size, number of metastatic lymph nodes, and clinical stage." (PMID 23620774, 2013).
breast carcinoma (continued). "To determine if there is a link between FOXF2 mRNA levels in primary tumors and clinicopathological features of breast cancer, we used RT-QPCR to detect FOXF2 mRNA levels in primary breast cancer samples with different clinicopathological features." (PMID 23620774, 2013). "Therefore, in luminal breast cancer and basal-like breast cancer cells, FOXF2 differentially modulates the transcription of WNT2B and FZD1 by enlisting NCoA3 and NCoR1, respectively." (PMID 40003882, 2025). "Additionally, the study also explores the frequent silencing of FOXF2 in luminal and HER2-positive breast cancer, attributing it to the hypermethylation of the FOXF2 CpG-island-containing promoter." (PMID 40003882, 2025). "The actions of FOXF2 in BLBC cells are akin to those of FOXA1 in luminal breast cancer." (PMID 40003882, 2025). "DNMT1, DNMT3A and DNMT3B increased the DNA methylation of FOXF2 in breast cancer cells." (PMID 35620052, 2022). "However, the TFs such as KLF5 (52%), KLF1 (39%), and SMAD2::SMAD3::SMAD4 (31%) showed significant enrichment (q < 0.1) in gained peaks and FOX family of TFs (FOXA1 28%, FOXA2 28% and FOXF2 17%) in lost peaks in breast carcinomas." (PMID 34090364, 2021). "Additionally, more small RNAs targeting FOXF2 in common diseases are waiting to be discovered, and the function of FOXF2 in lung cancer and breast cancer is still controversial." (PMID 33717680, 2021). "However, FOXF2 shows two opposite effects in breast cancer and lung cancer, serving as either a tumor-promoter or a tumor-suppressor by regulating cell cycles and metastasis." (PMID 33717680, 2021). "FOXF2 can play a dual role in the development of breast cancer by mediating TGF-β or MAZ." (PMID 32503970, 2020). "FOXF2 promotes invasion, migration and metastasis of breast cancer cells." (PMID 32503970, 2020). "A set of BRGs was identified as coexpression with FOXF2 in breast cancer tissues." (PMID 31222004, 2019). "Our in vitro data suggest that ectopic expression of FOXF2 in luminal breast cancer cells not only promotes bone metastasis but also may enhance non-bone metastatic potential under conditions of stromal cell induction." (PMID 31222004, 2019). "Our findings suggest that targeting the FOXF2-BMP/SMAD axis might be a promising therapeutic strategy to manage breast cancer bone metastasis." (PMID 31222004, 2019). "Because the bone metastasis of breast cancer cells results in osteolytic lesions, we tested whether FOXF2 drives cancer cells to induce osteoclastogenesis." (PMID 31222004, 2019). "Thus, antagonism between BMP/SMAD and TGF-β/SMAD plays a critical role in the FOXF2-regulated organotropism of breast cancer metastasis." (PMID 31222004, 2019). "Moreover, consistent with our finding that Foxf2 predicts poor survival in a subset of breast cancer patients, our results identify Foxf2 as a promigratory and prometastatic factor." (PMID 30285803, 2018). "Similarly, in a large tumor collection from the Metabric consortium, high Foxf2 expression predicted worse survival in the luminal B breast cancer subtype." (PMID 30285803, 2018). "Interestingly, the opposite is found in more progressive breast cancers, where high Foxf2 expression correlates with poor prognosis." (PMID 30285803, 2018). "In addition, we also tested the functions of FOXF2 on luminal breast cancer cells by ectopically expressing FOXF2 in MCF-7 cells." (PMID 25848863, 2015). "However, little is known about the correlation between FOXF2 expression and tumor progression and metastasis in breast cancer." (PMID 23620774, 2013). "In this study, FOXF2 mRNA levels in 305 primary breast cancer tissues were examined using RT-QPCR." (PMID 23620774, 2013). "However, the relationship between FOXF2 expression and breast cancer progression, metastasis, and prognosis, remains to be elucidated." (PMID 23620774, 2013). "However, another study found that FOXF2 promoted the bone metastasis of breast cancer cells." (PMID 34645493, 2021).